FAM41C (family with sequence similarity 41 member C)
Gene: Long non-coding RNA gene on chromosome 1 (868,052 to 877,032, reverse strand). Ensembl gene ENSG00000230368.
Diseases named in the same sentence as FAM41C in open-access papers:
FAM41C is named in the same sentence as 4 diseases in open-access papers, as found by Europe PMC text mining. Sharing a sentence is not in itself a finding about the gene and the disease. The quoted sentences say what the papers report.
melanoma (1 paper, 2019). A malignant, usually aggressive tumor composed of atypical, neoplastic melanocytes. "AL118505.1, LINC01527, AL512274.1, LINC01215, AC012313.4, FAM41C, SSTR5-AS1, were significant both in co-expression network and predicting survival rate, which may show powerful evidence for the metastasis of melanoma." (PMID 31024618, 2019).
metastatic melanoma (1 paper, 2024). A melanoma that has spread from its primary site to another anatomic site. "Six of these lncRNAs - AC068594.1, C7orf71, FAM41C, GPC5-AS1, MUC19, and LINC00402 - were correlated with survival time in metastatic melanoma patients." (PMID 39764216, 2024).
FAM41C also shares sentences with these, for which no sentence is quoted: seminoma (1 paper); tumor (1).